Y_RNA (Y RNA )
Gene: Miscellaneous RNA gene on chromosome 1 (28,985,710 to 28,985,810, forward strand). Ensembl gene ENSG00000206704.
Homologues: Orthologues: chimpanzee Y_RNA (96% identical), macaque Y_RNA (91% identical). Paralogues in human: Y_RNA (89% identical), RNY3 (88% identical), Y_RNA (88% identical), RNY3P1 (87% identical), Y_RNA (87% identical), Y_RNA (86% identical), Y_RNA (85% identical), RNY3P14 (84% identical), Y_RNA (84% identical), RNY3P5 (83% identical), Y_RNA (83% identical), RNY3P11 (82% identical), and 95 more.